ERBB2 (erb-b2 receptor tyrosine kinase 2)
Diseases named in the same sentence as ERBB2 in open-access papers (continued):
Sharing a sentence is not in itself a finding about the gene and the disease.
breast cancer (continued). "Additionally, in mouse mammary tumor virus erbB2 female transgenic mice administrated with different doses of 17β-oestradiol, it was found that the breast cancer incidence of mice was reduced by soybean diet in a high-oestrogen environment, but increased in a low-oestrogen environment." (PMID 28698459, 2017). "However, it is still largely unknown how specific miRNA functions affect ERBB2-positive breast cancers." (PMID 29089858, 2017). "Taken together, these data demonstrate that brief treatment with EGFR/erbB-2-targeting agents before the onset of tumors may provide lifelong protection from mammary tumors, through the concurrent inhibition of erbB-2 and ER signaling pathways and consequential reprogramming." (PMID 28061785, 2017). "This study addressed the question whether the recently developed molecular in vitro diagnostic MammaTyper® test could improve the reproducibility of the assessment of the four key routine breast cancer biomarkers ERBB2 (HER2), ESR1 (ER), PGR (PgR), and MKI67 (Ki67)." (PMID 28490348, 2017). "Thus, Mek activity is required for ErbB2 expression in breast cancer cells detached from the ECM." (PMID 29285258, 2017). "Our results also indicate that the erbB-2-overexpressing subtype of breast cancer may be more susceptible to the anti-cancer effects of buformin, due to the inhibition of numerous signaling molecules associated with RTK, especially erbB-2, signaling pathways." (PMID 28193239, 2017). "Indeed, our data provide the first evidence, to our knowledge, that a gene in the ERBB2 amplicon may counteract ERBB2 oncogenic properties in breast cancer." (PMID 28300085, 2017). "Our findings point to a specific role of p140Cap in curbing the aggressiveness of ERBB2-amplified breast cancers and suggest that, due to its ability to impinge on specific molecular pathways, p140Cap may represent a predictive biomarker of response to targeted anti-ERBB2 therapies." (PMID 28300085, 2017). "Thus, expression of MiR-125b and ERBB2 in breast cancer was investigated." (PMID 28738804, 2017). "Furthermore, in a panel of different breast cancer cell lines, the efficacies of the ErbB2-targeting drugs trastuzumab, pertuzumab and lapatinib were highly dependent on whether the cells were cultured as 2D monolayers or embdedded in 3D laminin-rich ECM gels." (PMID 29296175, 2017). "Mutations in EGFR, ERBB2, Erb-B2 receptor tyrosine kinase 3 (ERBB3) and Erb-B2 receptor tyrosine kinase 4 (ERBB4) (referred to hereinafter as ERBB family mutations) either occur alone or co-occur with PIK3CA mutations in 19% of HER2-positive breast cancers (n = 58)." (PMID 28750640, 2017). "To test whether ERRF is functionally involved in drug sensitivity, we restored ERRF expression by lentiviral infection in JIMT-1, a lapatinib resistant, ERBB2 positive breast cancer cell line that expressed a lower level of ERRF, and measured cell survival in both 2-D and 3-D cultures." (PMID 28415602, 2017). "Triple-negative breast cancer (TNBC) comprises 15–20% of all breast cancers (BCs) and is defined by a lack of estrogen and progesterone receptor expression and the absence of ERBB2 gene amplification, which encodes human epidermal growth factor receptor 2 (HER2)." (PMID 28636652, 2017). "Interestingly, the percentage of cells displaying nuclear GLI1 staining positively correlated with ErbB2 expression in carcinoma samples (p = 0.027), and this result suggests the involvement of Hh pathway activation in the development of ErbB2-positive breast cancer." (PMID 26843616, 2016). "Thus, it can be concluded that combinatorial treatment with these three mAbs may lead to a better therapeutic outcome for ErbB2-overexpressing breast cancer patients than trastuzumab plus pertuzumab." (PMID 26999718, 2016).
breast cancer (continued). "Furthermore, EGFR with ERBB2 are target genes of Lapatinib - Breast cancer drug." (PMID 26892392, 2016). "In breast cancer cells, Slk could activate HER2/Neu/ErbB2 for driving chemotaxis." (PMID 27699085, 2016). "However, it is important to note that upon amplification of the ERBB2 gene, which occurs frequently in breast cancer, the highly elevated levels of ErbB2 lead to violation of these physiological constraints and allow the formation of both ErbB2 homo-dimers and ligand-independent heterodimers." (PMID 27597943, 2016). "Another similarity is that β1 and β4 Integrin are important regulators of breast development and may play a role in breast tumour progression: β4 overexpression correlates with more rapid breast cancer progression and is required for ErbB2-driven tumorigenesis." (PMID 27348469, 2016). "Similarly, it has been demonstrated that the down-regulation of ErbB3 expression, and of its downstream pathways, by the HDACi SNDX-275, is a crucial mechanism to overcome the resistance to the anti-ErbB2 antibody trastuzumab in an ErbB2-overexpressing breast cancer model." (PMID 26862736, 2016). "However, to make the story more complex, the polyubiquitination of ERBB2 was proposed to either induce proteasomal degradation of ERBB2, to enable internalization and lysosome degradation, or to promote a selective autophagy of ERBB2 in breast cancer cells." (PMID 27863425, 2016). "However, the recent data from a large prospective study of early stage ERBB2-positive breast cancer indicate that patients with and without PTEN deficiency by immunohistochemistry derived benefit from treatment with trastuzumab." (PMID 27576528, 2016). "However, some breast cancer cells, particularly the breast cells that express low levels of ErbB2, such as MCF7, T47D and BT20 cells, are quite resistant to alcohol exposure; the short-term treatment of alcohol has little effect on their migration/invasion behavior." (PMID 26655092, 2016). "However, it remains unclear whether erbB3- and IGF-1R-initiated signaling pathways possess distinct effects on the sensitivity of lapatinib, a dual tyrosine kinase inhibitor against both EGFR and erbB2, in trastuzumab-resistant breast cancer." (PMID 26621843, 2016). "The H2-18 antibody might be a promising agent for treating ErbB2-overexpressing breast cancer." (PMID 27564098, 2016). "In parallel, it has been recently proposed in SKBR3 breast cancer cells that ErbB2 degradation is proteasome independent and that the conjugation of K63-linked polyubquitin chains to ErbB2 might be relevant to target its degradation by the autophagy-lysosomal system." (PMID 26716506, 2016). "Moreover, a 13-gene signature predicting rapid development of brain metastases in patients with ErbB2-positive advanced breast cancer may be useful in the design of preventive therapies." (PMID 26497551, 2015). "In addition, use of the BRD4 inhibitor JQ1 in combination with the EGFR inhibitor lapatinib has been shown to suppress lapatinib-induced kinome reprogramming in ERBB2+ breast cancer cells, where other kinase inhibitor combinations could not5." (PMID 26596901, 2015). "In addition, overexpression of ErbB2 diminished the binding of c-Met to plexin B1, suggesting that in breast cancer cells and in prostate cancer cells, ErbB2 and c-Met are competing for plexin B1 binding, which largely determines the cellular outcome of Sema4D signalling." (PMID 28536399, 2015). "The current standard of care requires all newly diagnosed cases of invasive breast cancer to be routinely tested by immunohistochemistry (IHC) for the expression of estrogen receptor alpha (ER), progesterone receptor (PR) and the growth factor receptor HER2/neu (ERBB2)." (PMID 26717565, 2015). "Thus, we wondered whether different levels of ErbB2 expression in tumors might also contribute to variations in breast cancer pathophenotypes in mice." (PMID 25853295, 2015).
breast cancer (continued). "For example, in breast cancer, recent studies that are mainly based on microarray-based gene expression data and unbiased hierarchical clustering have identified several molecular subtypes: basal-like, ErbB2+, normal breast-like, luminal subtype A, and luminal subtype B." (PMID 26539502, 2015). "Thus, combination treatment of lapatinib and trametinib may be a therapeutic option in treating hypoxic ERBB2-positive breast cancer cells." (PMID 25596742, 2015). "Consequently, the more prevalent Epi Luminal-B and ERBB2+ breast cancers give rise to poorer survival curves in Epi breast cancer cohorts, suggesting that heterogeneity within a cancer type could mask and perplex the role of EMT." (PMID 25214461, 2014). "Breast cancer is a heterogeneous disease which, according to extensive gene expression profiling, can be grouped into 4 major categories: luminal A, luminal B, human epidermal growth factor receptor-2 oncogene (also called Her2/ERBB2) type and basal-like breast cancer." (PMID 24693876, 2014). "However, whether MM-121 has the therapeutic potential to overcome resistance to trastuzumab or chemotherapy, like paclitaxel in erbB2+ breast cancer cells remains unclear." (PMID 24886126, 2014). "Thus, erbB3 receptor may serve as a useful biomarker for modulating tamoxifen sensitivity in luminal B (ER+, erbB2+) breast cancer and AWT in CRPC." (PMID 24886126, 2014). "As expected, the total levels of the AKT1 protein are elevated in all mammary tumor subtypes, but the activation of this kinase varies significantly and is highest in tumors with a known hyperactivation of the PI3 kinase in response to ERBB2 overexpression or loss-of-function of PTEN." (PMID 24628780, 2014). "The interaction of photo-activated 8MOP with regulatory elements within the ErbB2 catalytic kinase domain may explain the marked inhibition of ErbB2 signaling in PUVA-treated ErbB2+ breast cancer cells, including those that have developed resistant to current FDA-approved ErbB2 targeted therapies." (PMID 24551203, 2014). "Using the median H-score of 30 as threshold, TweakR was considered as positive in 12/31 ERBB2 positive carcinomas (39%), 14/39 basal-like tumors (36%), 12/28 luminal A tumors (43%), and 22/36 luminal B tumors (61%), with an overall positive expression in 45% of all tested samples of breast cancer." (PMID 25375638, 2014). "Finally, we found various correlations among model parameters which cannot be directly inferred from the available biological data and these dependencies were used to characterize the dynamics of cancer subpopulations during the initial phase of ErbB2+ mammary cancer progression." (PMID 25184361, 2014). "P95 ErbB2 is mainly expressed in aggressive breast cancers with lymph node metastases and its expression is an independent prognostic factor for ErbB2-positive breast cancer cases with significantly worse outcome, and predicts resistance to therapeutic ErbB2 inhibition." (PMID 24709902, 2014). "Interestingly, β1-integrin and β4-integrin- heterodimers are both expressed by breast epithelial cells (mostly as α3β1 and α6β4) and have been shown to be required for tumorigenesis and metastasis in the MMTV/PyMT and MMTV/Neu (rat homolog of ErbB2) mouse models of breast cancer, respectively." (PMID 25012362, 2014). "While the mechanism of AXL overexpression upon acquired resistance remains unclear in vivo, one study suggests that hypomethylation of the AXL promoter may play a role in AXL overexpression in ErbB2-positive breast cancer cells upon acquisition of resistance to the ErbB2 inhibitor, lapatinib." (PMID 25337673, 2014). "Thus, when we evaluate the impact of erbB3 on clinical outcome of breast cancer patients, it would be better to consider not only its expression and interactions with other RTKs like erbB2, but also its subcellular distribution as well as the expression levels of HRG." (PMID 24886126, 2014).
breast cancer (continued). "Therefore, ErbB2+ human breast cancers may have a different cell of origin from the Wnt-signaling active, basal-like subtype of human breast cancer." (PMID 24265712, 2013). "Several array comparative genomic hybridization (aCGH) studies of breast tumors and breast cancer cell lines point to commonly observed gains and losses on regions of chromosome 8, 13 and 17 – regions known to contain breast cancer associated genes such as BRCA2, ERBB2 and MYC." (PMID 23382830, 2013). "To study the molecular mechanism by which MM-121 overcomes paclitaxel resistance and increases paclitaxel-mediated anti-proliferative/anti-survival effects in the studied erbB2-overexpressing breast cancer cell lines, we investigated whether MM-121 might enhance paclitaxel-induced apoptosis." (PMID 24168763, 2013). "However, whether MM-121 holds potential to overcome trastuzumab resistance and enhance trastuzumab-mediated growth inhibition in erbB2+ breast cancer cells remains unclear." (PMID 24215614, 2013). "In addition, it is observed for the first time that serum CK levels were significantly associated with ERBB2+ breast cancer, but not other molecular subtypes." (PMID 23614022, 2013). "Thus, both our in vitro and in vivo data seem to indicate that the ability of MM-121 to enhance the therapeutic efficacy of paclitaxel against erbB2-overexpressing breast cancer may be restricted to the ineffective doses of paclitaxel." (PMID 24168763, 2013). "To explore whether the anti-erbB3 Ab MM-121 may enhance the activity of trastuzumab against erbB2+ breast cancers, we investigated the combinatorial effects of MM-121 and trastuzumab on erbB3 signaling and cell proliferation in two erbB2+ breast cancer cell lines (SKBR3 and BT474)." (PMID 24215614, 2013). "AR signaling effects on breast cancer progression may depend on ERα and ERBB2 status." (PMID 23593223, 2013). "At this moment, it remains unclear whether activation of the PI-3 K/Akt signaling by any means, such as PIK3CA mutation or phosphatase and tensin homolog (PTEN) deletion in addition to erbB2/erbB3 receptors, would also enhance expression of Survivin in breast cancer cells." (PMID 24168763, 2013). "This novel regulatory link, as well as the marked reduction in patient survival time associated with increased glutamine pathway gene expression, suggests that targeting glutamine metabolism may have therapeutic potential in the treatment of ERBB2+ breast cancer." (PMID 24304688, 2013). "Down-modulation of miR-181a inhibits TGF-β mediated EMT, invasion and migration, also reverting anoikisis resistance in breast cancer cells; high levels were then associated with shorter disease-free survival of breast cancer patients, who tested negative for ErbB2 amplification." (PMID 24284394, 2013). "FOXP3 acts as a transcriptional repressor of oncogenes, HER-2/ErbB2 and S-phase kinase-associated protein 2 (SKP2), and FOXP3-regulated microRNAs suppress special AT-rich sequence-binding protein 1, whereas deletions of FOXP3 exons extinguish those suppressive function in a breast cancer cell line." (PMID 24155921, 2013). "Current knowledge describes breast cancer as a heterogeneous disease classified in four major categories, i.e. basal-like, ErbB2 enriched, luminal subtype A or luminal subtype B. The majority of human breast cancers are hormone-receptor positive and may respond to endocrine therapy." (PMID 24764488, 2013). "Furthermore, serum CK levels were significantly associated with ERBB2+ breast cancer not HR+/ERBB2- or triple negative breast cancer." (PMID 23614022, 2013). "A deeper analysis of the percentage of cat mammary lesions with erbB-2 overexpression obtained in previous works and in the present manuscript demonstrates that with more recent techniques, it appears likely that a low percentage of cat mammary carcinomas overexpress the erbB-2 protein." (PMID 24386251, 2013).
breast cancer (continued). "Importantly, this recapitulates the regressions also seen in ERBB2-positive breast cancer patients." (PMID 22621282, 2012). "To accomplish this, we first intercrossed the mouse mammary tumour virus (MMTV)-activated ErbB2 strain (NDL2-5) to separate strains of mice bearing the MMTV-Cre and conditional FAK alleles and monitored virgin female cohorts for the development of mammary tumours." (PMID 22373082, 2012). "More importantly, the co-expression of TWIST1 and IL8 is correlated in the basal and ERBB2 subtypes, the two most aggressive subtypes of human breast cancers, supporting the important roles of the transcription factor and the cytokine in the pathology of advanced breast cancers." (PMID 22891766, 2012). "Both of these BL breast cancer cell lines demonstrate over-expression of ErbB1 suggesting that ErbB1 may hetero-dimerize with low levels of endogenous ErbB2 (forming an ErbB1/ErbB2/EphrinB1 complex) and mediate signaling from the complex." (PMID 22279592, 2012). "2/1 and HH-16.cl.4 rat mammary cell lines, complemented with expression profiling analysis of the Mycn and Erbb2 oncogenes and verification of the influence of global demethylation on the expression of these genes validates the use of these cell lines as models for breast cancer research." (PMID 22253826, 2012). "Notably, the dogma of ErbB-2 action as a membrane tyrosine kinase which induces the activation of mitogenic signaling pathways to promote breast cancer growth, has been challenged by the demonstration that MembErbB-2 migrates to the nuclear compartment, where it acts as a transcription factor (TF)." (PMID 22356700, 2012). "Our findings on HGF-mediated recovery, extend the previously published results to mammary epithelial cells and ErbB2 mammary tumor cells, emphasizing the fact that molecular events present in non tumorigenic cells could be retained during tumor growth and become the basis for drug resistance." (PMID 23028720, 2012). "We have previously reported that induction of epidermal growth factor receptor and ErbB2 in response to antihormonal agents may provide an early mechanism to allow breast cancer cells to evade the growth-inhibitory action of such therapies and ultimately drive resistant cell growth." (PMID 21396094, 2011). "Mechanistically, ErbB2 and v-ras-mediated downregulation of α2-integrin expression has been shown to require the Sp1 transcription factor in human breast epithelial cells, an event that was tied to the disruption of tissue architecture observed in breast cancer." (PMID 22203845, 2011). "This is because it has also been shown that the luminal A (ERα/PR+, HER-2−) subtype of breast tumours, which represents ∼70% of breast cancers, might, after becoming resistant to antihormonal therapy such as tamoxifen or aromatase inhibitors, evolve to overexpress ErbB-2." (PMID 21847123, 2011). "We hypothesize that GLUT1 is a critical mediator of cell survival, proliferation, glucose uptake and aerobic glycolysis in breast cancer cells in vitro and in mammary tumors in vivo, and tested this hypothesis using ErbB2 or PyVMT overexpressing mouse mammary carcinoma cell lines and tumors." (PMID 21826239, 2011). "At present, the management of breast cancer patients takes into consideration a combination of clinical and histopathological characteristics, together with the measurement of estrogen (ER) and progesterone (PR) hormone receptors and Her2/ERBB2 overexpression/amplification." (PMID 21731642, 2011). "Hence, specifically targeting STAT3 in ErbB2-overexpressing breast cancer cells that contain activated STAT3 may inhibit ErbB2-mediated malignant phenotypes." (PMID 27713313, 2010). "Thus, the use of EDIAs, which recognise a different site on ErbB2, could prove to be effective for treatment of breast cancer that cannot be cured with trastuzumab." (PMID 20051960, 2010).